FGF21 (fibroblast growth factor 21)
Diseases named in the same sentence as FGF21 in open-access papers (continued):
Sharing a sentence is not in itself a finding about the gene and the disease.
metabolic syndrome (continued). "Several studies have demonstrated a beneficial impact of FGF-21 analogs in dyslipidemia in people living with T2D and obesity." (PMID 40943107, 2025). "Typically, hepatic FGF21 production is induced under metabolic challenges such as fasting, high-fat or low-protein diets, and metabolic syndromes, including MAFLD." (PMID 41516073, 2025). "Emerging evidence also suggests that the gut-derived hormone fibroblast growth factor 21 (FGF21), which is modulated by plant-based nutrient intake, plays a role in improving insulin sensitivity and energy expenditure in individuals with metabolic syndrome." (PMID 40871683, 2025). "The concentrations of FGF-21 were elevated in individuals diagnosed with metabolic syndrome (335.80 pg/mL [IQR = 206.22–488] compared to 166.32 pg/mL [IQR = 135.70–256.61], p < 0.001)." (PMID 40559404, 2025). "Clinically, although phase II trials of FGF21 analogs (e.g., efruxifermin) demonstrate significant urate-lowering efficacy in metabolic syndrome cohorts, our genetic evidence advocates for stratified intervention strategies." (PMID 40388724, 2025). "In leptin-deficient (ob/ob) mice and diet-induced obese mice, the pharmacological effects of FGF21 on glucose, dyslipidemia, and IR are reduced." (PMID 40881124, 2025). "Blood FGF21 level is widely used as a biomarker in clinical studies, particularly in metabolic syndrome." (PMID 40563517, 2025). "Altered expression levels of fibroblast growth factor 21 (FGF21) have been detected in patients with metabolic syndrome." (PMID 38541057, 2024). "FGF21 relieved numerous inflammation-related metabolic disorders, including metabolic syndrome and cardiovascular diseases." (PMID 38721616, 2024). "Although many aspects still need to be addressed, FGF21 is still an ideal target for the treatment of metabolic syndrome." (PMID 37576954, 2023). "Here, we summarize the current research on the role of FGF21 in metabolic syndrome to explore the potential of FGF21 as a potential therapeutic target for metabolic syndrome." (PMID 37576954, 2023). "Although the results were surprising, the use of FGF21 is as a treatment for metabolic syndrome still requires further investigation." (PMID 37576954, 2023). "The analogs and mimetics of FGF19 and FGF21 have been repeatedly observed to improve dyslipidemia and NAFLD in multiple clinical trials." (PMID 36902015, 2023). "In agreement with our results, previous studies have established some associations of FGF21, HGF, and VEGF with metabolic syndrome and its various components." (PMID 38092892, 2023). "Fibroblast growth factor 21 (FGF21), a member of the fibroblast growth factor family, alleviates multifarious metabolic disorders such as metabolic syndrome, cardiovascular diseases, and atherosclerosis." (PMID 35405926, 2022). "FGF21 can improve the status of various metabolic diseases; thus, our findings present wogonin as an attractive therapeutic for metabolic syndromes." (PMID 36235573, 2022). "In the case of metabolic syndrome, these observations raise questions about the expression and the role of the endocrine FGF21 factor in sperm." (PMID 35282437, 2022). "Taken together, these findings put forward several potential mechanisms whereby FGF-21 induces dyslipidemia in patients with hypothyroidism." (PMID 34784265, 2022). "Fibroblast growth factor 21 (FGF21) is closely associated with metabolic syndrome (MetS)." (PMID 36474191, 2022). "Several parameters including CAL, number of teeth, and dyslipidemia demonstrated a correlation to serum FGF21 level." (PMID 36474191, 2022). "Hepatocyte NAMPT overexpression induced FGF21 and adipose browning, improved glucose homeostasis, and attenuated dyslipidemia in obese mice." (PMID 35228549, 2022). "The four Lipid parameters (total cholesterol, LDL, HDL, and TGs) and body weight showed statistically different compared to baseline, which was consistent with the results of FGF21 or LY2405319 administration to obese rhesus monkeys with dyslipidemia." (PMID 36618930, 2022).
metabolic syndrome (continued). "Among different members, FGF21 is a novel discovered cytokine which is significantly increased under the status of multiple lipid disorder diseases, such as dyslipidemia, obesity, and coronary artery diseases (CADs)." (PMID 34784265, 2022). "Due to the cytokine's stimulatory role in glucose uptake, there have been promising findings in the form of dyslipidemia improving outcomes from several of the clinical trials that are developing long‐acting FGF‐21 analogs." (PMID 36467791, 2022). "Similar to our findings of a more pronounced postprandial response to a mixed meal in IR, plasma FGF21 excursions after pure fructose or glucose ingestion have been found to be larger in individuals with metabolic syndrome compared to healthy individuals." (PMID 36501091, 2022). "In a pathologic condition such as metabolic syndrome, FGF21 increase to compensate for oxidative stress, ER stress, and mitochondrial dysfunction; thus, higher serum levels reflect uncompensated metabolic stress." (PMID 35663311, 2022). "Recently, the evaluation of serum levels of adiponectin and fibroblast growth factor 21 (FGF21) has been considered a valid tool for identifying the presence of metabolic syndrome in children." (PMID 36140410, 2022). "The concentration of FGF21 has been shown to be increased in several aspects of metabolic syndrome, indicating the presence of a compensatory response to higher metabolic stress or resistance to FGF21." (PMID 35323680, 2022). "The elevation of FGF21 by long-acting FGF21 analogs shows significant improvements in dyslipidemia and hepatic fat fractions in nonalcoholic steatohepatitis patients." (PMID 36093108, 2022). "Several clinical trials using FGF21 analogues or new recombinant PEGylated human FGF21 have shown an improved dyslipidemia, body weight, adiponectin levels and fasting insulinemia, but unfortunately a low effect on the glycemic control." (PMID 35409319, 2022). "In their study, circulating FGF-21 was a significant predictor, like dyslipidemia and hypertension, of subclinical atherosclerosis." (PMID 33810243, 2021). "Previous studies have demonstrated that plasma FGF21 concentrations are increased in metabolic syndrome and correlate with insulin resistance." (PMID 33846498, 2021). "Our previous study showed that FGF21 levels correlated with adiponectin, a metabolic syndrome-related cytokine that also has protective effects, including anti-inflammatory, anti-atherogenic, and anti-diabetic effects." (PMID 34799626, 2021). "Anti-inflammatory treatment with both, IL-1 antagonism and corticosteroids reduced FGF21 levels at short-term in individuals with the metabolic syndrome." (PMID 33846498, 2021). "In this context, several current drugs used for treatment inDM type 2 are highly effective for glucose lowering, but lack the considerable therapeutic effects of FGF21 on dyslipidemia." (PMID 34573919, 2021). "Dyslipidemia in the context of hypothyroidism constitutes another source of FGF-21 levels discrepancy among different studies." (PMID 34946319, 2021). "For CVDs, metabolic syndrome is a well-known precursor, which suggests a possible link of FGF21 to CVDs." (PMID 34513950, 2021). "In recent years, there has been a lot of evidence to suggest that that increased serum FGF21 levels are found in obese, insulin-resistant patients, and those with metabolic syndrome." (PMID 34573919, 2021). "Herein, we report the results of two clinical trials investigating the effects of short- and longer-term IL-1 antagonism as well as acute corticosteroid treatment on levels of FGF21 in obese patients with the metabolic syndrome." (PMID 33846498, 2021). "The aim of this study was to investigate effects of two different anti-inflammatory treatments (IL-1 antagonism or high-dose corticosteroids) on FGF21 in patients with the metabolic syndrome." (PMID 33846498, 2021).
metabolic syndrome (continued). "As a consequence, we postulated that antagonism of the IL-1β inflammatory pathway would lower FGF21 levels in patients with the metabolic syndrome." (PMID 33846498, 2021). "FGF21, as a hormone regulating stress responses, is well known for relieving numerous metabolic disorders related to inflammation, including metabolic syndrome and cardiovascular diseases." (PMID 34800969, 2021). "We previously reported that FGF21 levels were high in smokers and negatively correlated with the metabolic syndrome-related cytokine, adiponectin." (PMID 34799626, 2021). "A recent study also found that FGF21 treatment reduced the aortic sinus plaque area and ameliorated dyslipidemia in ApoE−/− mice." (PMID 32957703, 2020). "FGF21 analogs tested as antidiabetic drugs in obese and overweight humans reduced dyslipidemia and steatosis." (PMID 32546231, 2020). "Some studies suggest that adipose-derived FGF21 is a marker of metabolic stress, as it has been shown to correlate with features of the metabolic syndrome." (PMID 32158768, 2020). "FGF21 analogs with balanced receptor agonism and sustained exposure have also been shown to improve glycemic control, ameliorate dyslipidemia and reduce body weight." (PMID 33381084, 2020). "FGF21 is a direct target of PPARα, and pemafibrate increases fasting and postprandial FGF21 levels along with improving dyslipidemia in humans." (PMID 31766193, 2019). "Obese patients with metabolic syndrome had a higher level of FGF21, which correlates with blood glucose and BMI levels." (PMID 30959789, 2019). "A large Chinese prospective study has found that increase of FGF21 levels positively correlated with hyperglycemia and dyslipidemia in pre-diabetic subjects of normal phenotype." (PMID 30927227, 2019). "Fibroblast growth factor 21 (FGF21) emerges as an insulin-mimetic hormone that regulates systemic energy balance and has beneficial effects on body weight, insulin sensitivity, dyslipidemia, and pancreatic β-cell growth." (PMID 28677104, 2018). "Elevated level of circulating FGF21 was correlated with the incidence of hypertension in community-dwelling adults and dyslipidemia in CHD patients." (PMID 30185439, 2018). "Numerous studies have revealed the pharmaceutical importance of FGF21 for treating metabolic syndrome, which is due to its strong insulin-sensitizing and thermogenic effects on adipose tissues." (PMID 28129657, 2017). "Lots of breakthroughs were made and FGF21 was considered as a drug candidate for some metabolic syndromes." (PMID 29109955, 2017). "In human adipocytes, FGF21 has been shown to attenuate lipolysis and an FGF21 analog has been demonstrated to ameliorate dyslipidemia in human subjects." (PMID 27583452, 2016). "The failure of endogenous FGF21 to improve these metabolic syndromes implied a FGF21-resistant state due to impaired FGF21 action." (PMID 26914024, 2016). "Serum levels of FGF-21 have been shown to increase in subjects with metabolic syndrome and atherosclerosis." (PMID 26382974, 2015). "The clarification of the molecular mechanism underlying the effects that FGF-21 plays in dietary interventions in NEB and its potential in the treatment of metabolic abnormalities in dairy cows with metabolic syndrome require further investigation." (PMID 26497746, 2015). "Due to the increasing frequency of metabolic syndrome in the pediatric population, and as FGF21 studies in children are limited, we investigated baseline serum levels of FGF21 in healthy children during an oral glucose tolerance test." (PMID 24883065, 2014). "An alternative approach to treat metabolic syndrome is to develop drugs or nutritional supplements that induce a sustained increase endogenous FGF21 production." (PMID 24733293, 2014). "We propose that this insulin/glucagon synergism plays a role in mediating the elevation in FGF21 production during starvation and conditions related to metabolic syndrome." (PMID 24733293, 2014).
metabolic syndrome (continued). "One factor that has limited the development of exogenous FGF21 as a drug to treat metabolic syndrome is its short half-life in the circulation." (PMID 24733293, 2014). "High levels of FGF21 predicted impaired glucose metabolism (OR = 2.2; 95%CI 1.3–3.6; P = 0.002), metabolic syndrome (OR = 2.6; 95%CI 1.5–4.5; P = 0.001) and T2DM (OR = 2.4; 95%CI 1.2–4.7; P = 0.01) after adjustment for age, sex and BMI." (PMID 24260557, 2013). "Our group has found a direct relationship between FGF21 and BMI, uric acid, fasting glucose, and the components of the metabolic syndrome)." (PMID 22701542, 2012). "Several studies have shown increased plasma FGF21 levels in both obese and type 2 diabetic patients, which correlate with several factors involved in the metabolic syndrome, for example, nonalcoholic fatty liver disease and dyslipidemia." (PMID 23118742, 2012). "This also applies to the increase in FGF21 in MASLD related to metabolic syndrome." (PMID 41465464, 2025). "Furthermore, the development of T2D and the metabolic syndrome are predicted by the development of FGF21 resistance." (PMID 40040308, 2025). "Among participants who did not have the metabolic syndrome at baseline, higher FGF21 level was associated with the development of metabolic syndrome (quartile 4 vs. quartile 1, HR = 1.76 [95% CI 1.46–2.12])." (PMID 40356318, 2025). "The FGF21 hormone involved in regulating energy and glucose-lipid metabolism, predominantly expressed in the liver, adipose tissue, and skeletal muscle, is known to be modulated by exercise, offering potential benefits for individuals with metabolic syndromes." (PMID 40308270, 2025). "However, the mechanisms of FGF21 involved in the development and progression of metabolic syndrome especially in HP plus T2DM as yet unexplored." (PMID 37424900, 2023). "Moreover, the current research on FGF21 and metabolic syndrome is mostly in the basic experimental stage, and its clinical research needs to be further strengthened." (PMID 37576954, 2023). "Under the condition of dyslipidemia, a risk factor for atherosclerosis, HDL alone cannot improve the blood lipid profile of the body, and in this case, the compensatory increase of FGF21 level plays a role in improving blood lipid by increasing the reverse transport of cholesterol." (PMID 38057786, 2023). "Taken in the context of previously published human studies showing elevated FGF21 levels in patients with metabolic syndrome and HFpEF9,23,24, we proposed that FGF21 signaling is a conserved critical mechanism contributing to pathological concentric hypertrophy and heart failure." (PMID 35513431, 2022). "FGF-21 is an indicator of metabolic syndrome and endocrine dysfunction and BPA binding affinity to FGF-21 may be a novel mechanism of action of BPA in disrupting metabolic regulations leading to metabolic derangement in the body." (PMID 35648239, 2022). "Furthermore, chronic administration of FGF21 analogs ameliorates dyslipidemia and reduces body weight in obese and T2D patients, and also decreases fasting insulin levels while increasing adiponectin levels." (PMID 35563026, 2022). "The serum FGF21 levels also tended to be high in patients with dyslipidemia." (PMID 35574015, 2022). "The reduction in FGF21 is also in line with well-known anti-inflammatory functions of both EPA and DHA, since increased FGF21 levels have been associated with the presence of inflammatory chronic diseases, including metabolic syndrome." (PMID 36140410, 2022). "Interestingly, the serum FGF21 response to simple sugar intake is enhanced in subjects with metabolic syndrome compared to healthy subjects." (PMID 36235821, 2022). "In this context, increased serum FGF21 might be an indirect consequence of a compensatory up-regulation against a presence of dyslipidemia components as shown as the correlation analysis in this study." (PMID 36474191, 2022).
metabolic syndrome (continued). "As we known, the increased circulating FGF21 levels were positively correlated with metabolic syndrome in obese population, because the physiological increased dose of circulating FGF21 helps to maintain insulin sensitivity in specific tissues during the early stages of these diseases." (PMID 34912302, 2021). "Fibroblast growth factor-21 (FGF21) is elevated in patients with the metabolic syndrome." (PMID 33846498, 2021). "This suggests that metabolic syndrome is an FGF21-resistant state." (PMID 33210059, 2020). "However, the molecular mechanisms that influence the lipid profile in the non-fasting state are quite different between age, as well as the possible intervention of glucagon and FGF21 in the control of dyslipidemia." (PMID 31405194, 2019). "However, high serum FGF21 levels are found in obese subjects, it can be increased in subjects with other insulin resistant states such as dyslipidemia and coronary artery disease non-alcoholic fatty liver disease (NAFLD) and polycystic ovarian syndrome." (PMID 27471739, 2016). "Therefore, it is logically important to confirm and determine the role of FGF21 in the neurocontrol of blood pressure regulation and its contribution to the metabolic syndrome-related pathogenesis of hypertension." (PMID 27387420, 2016). "Furthermore, FGF21 is an important regulator of lipid and carbohydrates metabolism and a promising drug for treating metabolic syndrome." (PMID 25144734, 2014). "FGF21 has also drawn attention as a promising new approach to treat metabolic syndrome." (PMID 24733293, 2014). "FGF-21 is able to ameliorate dyslipidemia reducing TAG and LDL-c and increasing HDL-c." (PMID 25356508, 2014). "Furthermore, T2D and the development of the metabolic syndrome are predicted by FGF21 resistance." (PMID 40040308, 2025). "This study suggests that FGF21 might be a novel molecular target for metabolic syndromes." (PMID 35307922, 2022). "Therefore, it was possibly implied that individuals who had periodontitis might comprise a higher chance of dyslipidemia development, which subsequently increased an expression of FGF21 level as a protective role." (PMID 36474191, 2022). "FGF21 administration in obese mice alleviated hyperinsulinemia and dyslipidemia, indicating that the increased serum FGF21 found in our OB group may be a homeostatic compensation to the metabolic stress imposed by body fat accumulation in children and adolescents." (PMID 35740758, 2022). "Therefore, FGF21 has been considered as a new biomarker for metabolic syndrome." (PMID 34513950, 2021). "The aim of this study was to evaluate the relationship between serum FGF21 levels and metabolic syndrome (MetS) in T2DM patients." (PMID 31582974, 2019). "Increased fibroblast growth factor 21 (FGF21) levels have been found in patients with metabolic syndrome (MetS)." (PMID 29581470, 2018). "A recent study reported that fibroblast growth factor 21 (FGF21), which is a cytokine increased in dyslipidemia, was reduced in hypothyroidism patients compared to normal subjects." (PMID 35328405, 2022). "Fibroblast growth factor 21 (FGF21) is a member of the FGF superfamily that regulates metabolic homeostasis and is a potential therapeutic target for the treatment of metabolic syndrome." (PMID 31918921, 2020). "Additionally, FGF-21 levels may increase with stress, steatosis hepatis, or in metabolic syndrome." (PMID 29385732, 2018). "Fibroblast growth factor 21 (FGF21), a secretion protein, functions as a pivotal regulator of energy metabolism and is being considered as a therapeutic candidate in metabolic syndromes." (PMID 29109955, 2017). "Nutrition and PPAR alpha-Sirt 1 expression related to hepatic FGF21 production has become important to NAFLD and the metabolic syndrome." (PMID 28248224, 2016).